LGALS4 (galectin 4)
Diseases named in the same sentence as LGALS4 in open-access papers (continued):
Sharing a sentence is not in itself a finding about the gene and the disease.
cancer (continued). "Galectin-4 is largely expressed by intestinal epithelial cells and shows antagonist effects depending on the type of cancer." (PMID 27642006, 2016). "In the discovery samples, the proportion of carcinoma cells that showed strong expression of galectin-4 on immunohistochemical analysis was almost consistent with the expression levels of galectin-4 determined by western blotting." (PMID 24339976, 2013). "Immunohistochemical analysis showed cytoplasmic, nuclear, and membranous expression of galectin-4 in carcinoma cells; galectin-4 was frequently observed to localize much more frequently to the nucleus and cytoplasm than to the membranes." (PMID 24339976, 2013). "In cancer cell lines LGALS4 is expressed in highly differentiated cell lines which form polarized monolayers while undifferentiated cell lines do not express LGALS4 but Galectin1." (PMID 19903339, 2009). "This study, using dedicated-microarrays containing 6864 genes previously known to be involved in cancer, allowed us to select 5 genes (LGALS4, ACS5, CLU, SRI and CCT5) with significant differential expression between tumors and normal tissue." (PMID 19903339, 2009). "The preferential expression in malignant cells suggests that LGALS4 may play a critical role in tumorigenesis and cancer cell-specific metabolic or signaling pathways." (PMID 39857769, 2025). "Galectin-4 can form a bridge between cancer cells, vascular endothelium, and red blood cells." (PMID 36873388, 2023). "This characteristic of galectin-4 may be due, in part, to differences in the factors surrounding cancer tissues and cells, especially the molecules and glycans that interact with galectin-4." (PMID 37569679, 2023). "Our findings showed an interaction between cancer cells and erythrocytes via galectin-4." (PMID 37305017, 2022). "Displacement of galectin-4 to attachment points of cancer cells and erythrocytes was noticed." (PMID 37305017, 2022). "Among these cancers, only the role of galectin-4 in CRC development has been revealed explicitly." (PMID 27017379, 2016). "Furthermore, serum galectins, including galectin-4, have been shown to promote cancer cell adhesion to vascular endothelial cells in vitro, suggesting that circulating galectins have a metastasis-promoting effect." (PMID 24339976, 2013). "Therefore, the LGALS4 promoter might be a potential target site for advanced UC in cancer therapies." (PMID 28423602, 2017). "Moreover, galectin-4 has also showed contradictory roles in cancer which may depend on the types of cancer." (PMID 27017379, 2016). "Therefore, circulating level of galectin-4 might be a predictor for cancer patients, especially those with metastasis." (PMID 27017379, 2016). "Here, we identified galectin 4 (gal 4) as a cancer cell–produced protein that was deposited into the ECM of PDAC tumors and detected high-circulating levels of gal 4 in patients with PDAC." (PMID 36478037, 2023). "The mRNA expression level of FXYD3, LGALS4, USH1C, ECI2, TGM2, and HMGA2 genes which are involved in EMT, drug resistance, and cancer progression were measured in HCT116/OX-R4.3 and HCT116/OX-R10 cells by qRT-PCR." (PMID 37535601, 2023). "After the analysis of fold changes, upregulation in the mRNA level of LGALS1, LGALS3, LGALS4, LGALS8, and LGALS9 was detected in cancer patients compared to normal ovarian tissue." (PMID 36050693, 2022). "On the contrary, the expression level of the two other candidate markers LGALS4 and CEACAM6 display opposite trends, with higher levels in normal healthy blood compared to cancer blood." (PMID 26993598, 2016). "Comparing the total expression differences of the three target genes in all cells of cancer tissue and normal tissue, the results suggest that: AEN gene expression is higher in cancer tissue than normal tissue, while LGALS4 and XDH gene expression is lower in cancer tissue." (PMID 36589748, 2022).
cancer (continued). "Notably, mRNA and protein expressions of LGALS4, LGALS10 and LGALS13 were decreased in cancer cells than those in normal cells (P<0.05)." (PMID 33854625, 2021). "Interestingly, by combining TSPAN8 and LGALS4, which display specular expression in cancer and/or normal blood (TSPAN8 is higher in CRC blood, whereas LGALS4 is lower), we detected promising values of sensitivity and specificity compared to the markers alone." (PMID 26993598, 2016). "Furthermore, these PCa cell lines lacked ligands for EGFR, HER3, and IGF1R, and thus galectin-4 mediated receptor tyrosine kinase (RTK) phosphorylation was found to be the key interaction for promoting cancer metastasis." (PMID 32075174, 2020). "Although galectin-4 is not a universal and unambiguous marker in different types of cancers, it could be a helpful parameter in diagnosis of these tumors and clinical manifestations." (PMID 27017379, 2016). "In addition, only a small number of stromal cells around carcinoma cells expressed galectin-4, whereas no expression was detected in the immune cells surrounding carcinoma cells and normal lung tissues." (PMID 24339976, 2013). "Adjacent non-malignant tissues exhibited absent or markedly weaker expression for Galectin-4, Galectin-7, MUC21, ST6GALNAC1, and ST6GALNAC2 compared to the corresponding cancer tissues." (PMID 40718829, 2025).
infection (58 papers, 2007 to 2025). The state of being infected such as from the introduction of a foreign agent such as serum, vaccine, antigenic substance or organism. "We also observed infection-associated up-regulation of transcripts for two galectins, which belong to the C-type lectin family; galectin 1 (+1.5 fold), and galectin 4 (+1.6 fold)." (PMID 21682880, 2011). "We also observed infection-associated up-regulation of transcripts for two other galactose-binding lectins; galectin 1, which is thought to bind gastrointestinal mucins, and galectin 4, which has been shown to be localised to gastric mucous cells in mice." (PMID 21682880, 2011). "FREP 2 and 3, coagulation factor IX, dermatopontin, dual oxidase, galectin 4, MIF, peroxiredoxin, superoxide dismutase Cu-Zn, and heat-shock protein 70 all exhibited increased expression in snails that successfully resisted infection compared to those that were infected by S. mansoni." (PMID 22479663, 2012).
adenocarcinoma (3 papers, 2009 to 2025). A common cancer characterized by the presence of malignant glandular cells. "Galectin-4 expression was detected in 34 lepidic (17.0%), 60 acinar (28.4%), 21 papillary (27.3%), 9 solid (11.7%) and 1 micropapillary predominant adenocarcinomas (100%)." (PMID 24339976, 2013). "LGALS4 expression seems to be correlated to both histological type and the differentiation status of the adenocarcinoma." (PMID 19903339, 2009).
LGALS4 also shares sentences with these, for which no sentence is quoted: cyst (55 papers); retinal degeneration (31); tauopathy (12); Arrhythmia (8); Parkinson disease (8); brain tumor (7); neurodegenerative disease (7); Infertility (6); viral infection (6); bacterial infection (5); glioma (5); melanoma (5); neuroblastoma (5); chordoma (4); developmental delay (4); Huntington disease (4); leukemia (4); Alzheimer disease (3); cardiomyopathy (3); coronary artery disease (3); sterility (3); Stroke (3); testis tumors (3); Alexander disease (2); autism (2); breast tumor (2); cardiac arrhythmia (2); cardiovascular disease (2); colloid carcinomas (2); colon adenoma (2).
A further 125 diseases each share a sentence with LGALS4 in 2 papers or fewer.